SNORD115-17 (small nucleolar RNA, C/D box 115-17)
Synonyms: HBII-52-17
Gene: Small nucleolar RNA gene on chromosome 15 (25,201,323 to 25,201,404, forward strand). Ensembl gene ENSG00000201482.
Gene Ontology:
Biological process: RNA processing
Cellular component: nucleolus
Homologues: Paralogues in human: SNORD115-18 (100% identical), SNORD115-19 (100% identical), SNORD115-20 (98% identical), SNORD115-12 (96% identical), SNORD115-9 (96% identical), SNORD115-10 (95% identical), SNORD115-11 (95% identical), SNORD115-13 (95% identical), SNORD115-29 (95% identical), SNORD115-36 (95% identical), SNORD115-40 (95% identical), SNORD115-42 (95% identical), and 37 more.